DCN (decorin)
Diseases named in the same sentence as DCN in open-access papers (continued):
Sharing a sentence is not in itself a finding about the gene and the disease.
tumor (continued). "COL14A1 interacts with decorin, a small leucine-rich proteoglycan, which has incrementally been shown to be a powerful inhibitor of growth in a wide variety of tumor cells." (PMID 25050929, 2014). "Examining the Human Protein Atlas online database of immunostained tissue samples we have surveyed decorin expression in silico in several different tumor types, comparing them with corresponding normal tissues." (PMID 24634138, 2014). "Decorin expression in normal tissues was higher than in tumor tissues (P < 0.001, Wilcoxon signed-rank test; n = 35), whereas periostin expression was lower in normal tissues (P = 0.005, Wilcoxon signed-rank test; n = 35)." (PMID 25400079, 2014). "Collectively, the set of proteins that interact with decorin (the ‘interactome') generates a powerful antitumorigenic signal by potently repressing tumor cell proliferation, survival, migration, and angiogenesis." (PMID 25400079, 2014). "Previous studies have shown a decreased expression of decorin in the stroma of specific tumor types 26,27." (PMID 24634138, 2014). "We found that decorin is abundantly secreted and deposited in normal connective tissue but its expression is consistently decreased in the tumor microenvironment." (PMID 24634138, 2014). "Decorin is a powerful endogenous tumor repressor acting in a paracrine fashion to limit tumor growth and angiogenesis." (PMID 25244916, 2014). "As a result, decorin inhibited tumor growth in vivo, probably via the inhibition of the β-catenin pathway." (PMID 23296269, 2013). "Decorin has been found to have a tumour suppressor role in several studies, but other works and ours correlate decorin with increased tumour invasion and metastasis." (PMID 24142880, 2013). "The role of decorin in cancer progression and its therapeutic potential as a tumour suppressing antimetastatic agent has been the focus of numerous studies." (PMID 24146840, 2013). "Altogether, these data indicate that depending on the type and context of cancer analysed, decorin can have opposite roles on tumour progression." (PMID 24142880, 2013). "Decorin-expressing oncolytic Ad therefore led to dramatically increased anti-tumor effect as well as survival benefit in a variety of tumor xenograft models." (PMID 23898462, 2013). "Nevertheless, DSPGs expression were described to be increased in breast cancer fibroadenoma compared to healthy tissue, and, although the DSPG decorin was present in both healthy and tumor tissue, versican was exclusively detected in tumor samples." (PMID 23984412, 2013). "Lumican, another small leucine proteoglycan, has also been demonstrated to display dual anti- or pro-tumoural activity depending of tumour types and is highly correlated to decorin in human MIBC (R = 0.9)." (PMID 24142880, 2013). "We noticed in two independent experiments that growth of MB49-I-shDcn1 and MB49-I-shDcn2 correlated with their level of secretion of decorin, which indicates that decorin promotes MB49-I tumour growth in a dose-dependent manner." (PMID 24142880, 2013). "Of note, however, when comparing muscle-invasive to superficial tumours, the authors observed, like us, overexpression of decorin in MIBC." (PMID 24142880, 2013). "Several studies have demonstrated that de novo decorin expression in tumour cell lines can inhibit their proliferation in vitro." (PMID 24142880, 2013). "Although decorińs role in inhibiting tumour growth is recognized today, the origin of decorin expression in cancers has remained partially unsolved." (PMID 24146840, 2013). "While in several studies decorin has been found to have a tumour suppressor role, others correlate decorin with increased tumour invasiveness, metastases and angiogenesis." (PMID 24142880, 2013). "Very careful interpretation is applied in this case because of high variation of decorin and lumican levels in individual tumours, up to complete absence." (PMID 23691363, 2013).
tumor (continued). "Analysis of the protein by immunohistochemistry obtained from the human protein atlas portal confirmed overexpression of decorin in epithelial tumour cells as compared to normal epithelial cells." (PMID 24142880, 2013). "The results showed that the decorin and lumican proteins were expressed both in normal and tumour prostate tissues at the similar levels and localised mainly in tissue stroma but not in the prostate epithelial cells." (PMID 23691363, 2013). "Seemingly, our data presented above seem to contradict a recently published article indicating that decorin advocates for a more pro-inflammatory tumor microenvironment." (PMID 23029096, 2012). "Decorin exerts pleiotropic effects in tumour suppression, affecting multiple mechanisms and pathways." (PMID 22880013, 2012). "Decorin, a member of the small leucine-rich proteoglycan gene family, exists and functions wholly within the tumor microenvironment to suppress tumorigenesis by directly targeting and antagonizing multiple receptor tyrosine kinases, such as the EGFR and Met." (PMID 23029096, 2012). "An additional decorin-induced target classified as a tumor suppressor gene within the stroma, was Peg3 (paternally expressed gene 3, 2.49-folds, P = 0.0078) and it encodes a zinc finger transcription factor (Cys2His2 variety) of the Krüpple-type family." (PMID 23029096, 2012). "The anti-tumorigenic properties of decorin have been presented as a stromally derived tumor repressor that functions by directly binding to receptor tyrosine kinases situated on the tumor cell membrane." (PMID 23029096, 2012). "Collectively, these findings indicate that decorin is capable of targeting the tumor stroma in addition to the well-established anti-oncogenic activity targeting the carcinoma cells." (PMID 23029096, 2012). "In contrast, the number of genes derived from the tumor stroma of decorin-treated animals showed significant changes, with both upregulated and downregulated genes." (PMID 23029096, 2012). "We found that decorin protein core modulated the differential expression of 374 genes within the stromal compartment of the tumor xenograft." (PMID 23029096, 2012). "The predictors in the Cox models, and the partitioned gene sets in the figures, include three sets of genes (proliferation, stromal-decorin, and stromal-laminin), along with clinical measures, principally lymph node status and tumor size." (PMID 22719844, 2012). "The domain for the first is estrogen receptor-positive samples, using as predictors proliferation, stromal-decorin, and clinical descriptors (nodal status and tumor size)." (PMID 22719844, 2012). "When in soluble form, decorin inhibits tumor growth by downregulating several receptor tyrosine kinases (RTKs) such as the EGFR, IGF-IR, and Met primarily by evoking caveolin-mediated internalization and degradation." (PMID 23029096, 2012). "Decorin is a key modulator of the tumour microenvironment through interactions with EGFR and MAPK pathways." (PMID 22363530, 2012). "Analysis of these stromal genes in context of the co-culture via qPCR revealed a recapitulation of the expression patterns of Peg3, Bmp2k, and Zc3hav1 (P<0.001), the same stromal genes verified as induced by decorin within the tumor xenografts." (PMID 23029096, 2012). "Systemic treatment with decorin resulted in an induction of Peg3 as well as Bmp2k and Zc3hav1 within the tumor stroma as visualized via immunofluorescence and quantified using three-dimensional surface plots of the fluorescent signal." (PMID 23029096, 2012). "Adenoviral-mediated decorin gene delivery and/or via systemic treatment retards the growth of various tumor xenografts including squamous, breast, and prostate carcinomas." (PMID 23029096, 2012). "High DCN expression in stroma correlated with lower tumour grade (p<0.0001), Ki67 level ≤10% (p = 0.005) and ER positivity (p = 0.0002)." (PMID 22363530, 2012).
tumor (continued). "Subsequently, we injected ∼3 million MDA-231(GFP+) cells into the mammary fat pads of SCID mice (n = 6 each), and when the tumor reached palpable size we treated them with daily i.p. injections of recombinant decorin protein core (10 mg/Kg)." (PMID 23029096, 2012). "Decorin is also involved in the regulation of angiogenesis and blocks tumor cell-mediated angiogenesis by downregulating VEGFA production, as well as Met and downstream angiogenic networks." (PMID 23029096, 2012). "Decorin is normally present in the extracellular stromal compartment and has been shown to restrain growth of many tumor cells by down-regulating the epidermal growth factor receptor (EGFR)." (PMID 21958730, 2011). "In contrast, decorin, which is mainly over-expressed by activated fibroblasts in various cancer types, is considered to be a tumor suppressor proteoglycan." (PMID 21791066, 2011). "The accumulation of decorin was significantly related to higher expression of ERα (P = 0.02) and PR (P < 0.01) in tumor cells only in patients with MAMCs." (PMID 21791066, 2011). "Decorin is normally present in the extracellular stromal compartment and analysis of a variety of tumours indicates that it is seldom expressed by cancer tissue." (PMID 21958730, 2011). "Further support for decorin's anti-angiogenic properties comes from an in vivo study performed in nude mice that demonstrated decreased angiogenesis in tumor xenografts that over-express decorin." (PMID 22039486, 2011). "We also identified tumor specific increases of nidogen 1, decorin, perlecan, and of six laminin subunits." (PMID 21731504, 2011). "IHC results showed that positively stained decorin was detected in only 11.8% of the tumor tissues, significantly lower than that observed in normal alveoli tissues (53.1%, P < 0.001)." (PMID 22104218, 2011). "Decorin protein levels in tumor tissues and corresponding normal tissues from 16 cases of lung squamous cell carcinoma (SCC) were determined by Western blot analysis." (PMID 22104218, 2011). "Although, decorin is expressed in tumor stroma but it's rarely expressed by cancer cells and tissues themselves as has been demonstrated by analysis of a variety of tumors including colon, pancreas, prostate, lung, ovarian, breast cancer." (PMID 21958730, 2011). "Possibly estrogens mainly produced locally by stromal fibroblasts in early stages of breast carcinogenesis drive through paracrine action tumor growth and through autocrine mechanisms the biosynthesis of versican and decorin by themselves." (PMID 21791066, 2011). "Western blot results showed that decorin protein levels in 75.0% (12/16) of the SCC tumor tissues were lower than those of the corresponding normal lung tissues." (PMID 22104218, 2011). "Normal mammary glands (Group A) expressed the highest level of decorin mRNA among the three groups, and tumor tissues (Group C) expressed the lowest level." (PMID 20092659, 2010). "This hormone elicited marked increases in bone formation and increased numbers of mature osteoblasts, which express high levels of potential anti-tumor factors that include decorin, lumican, and CYR61." (PMID 21188144, 2010). "The expression of decorin, which is abundant in the stroma, can for example, indicate the prognosis of a tumor and decorin can also diminish tumor growth in rat experiments." (PMID 20398359, 2010). "Real-time PCR was performed to evaluate the expression level of decorin mRNA in mammary gland tissues and tumor tissue samples." (PMID 20092659, 2010). "When we looked for the function of these genes, we found that three (SLC26A3, TPM1, and DCN) of them play a tumour suppressor role." (PMID 19678923, 2009). "We detected significant previously undescribed underexpression in CRC for genes SLC26A3, TPM1 and DCN, with a suggested tumour suppressor role." (PMID 19678923, 2009). "Our results show that the DCN gene is 4.6 times (p < 0.01) underexpressed in tumour than normal tissue." (PMID 19678923, 2009).
tumor (continued). "The findings also provide interesting leads for further research into how DCN may interact with the immune microenvironment to promote tumour development and the emergence of chemoresistance." (PMID 41392017, 2026). "Decorin is a proteoglycan that suppresses tumor growth and angiogenesis." (PMID 42015278, 2026). "However, given that PDAC is typically considered an immunologically ‘cold’ tumour, characterised by a dense stroma, immune suppression and exclusion, it is likely that the activating effects of DCN on macrophages are overridden in this setting." (PMID 41392017, 2026). "Furthermore, it was shown that a recombinant oncolytic adenovirus carrying the human DCN gene suppressed tumor growth and skeletal metastases in a mouse model." (PMID 41470114, 2025). "CAFs and tumor cells were identified using DCN and KRT19, respectively." (PMID 40215177, 2025). "As the tumor differentiation degree decreased, DCN expression gradually reduced." (PMID 40109852, 2025). "In previous studies, decorin has been studied in its purified form also as a tumour suppressor." (PMID 41300368, 2025). "DCN also suppresses angiogenesis, tumor growth, and bone metastasis in PC models." (PMID 40841830, 2025). "In terms of the therapeutic potential of C2C12-EVs, the anti-tumour potential of decorin could be further tested by overexpressing decorin fused to an EV sorting domain to enable packaging of the overexpressed protein into nascent EVs." (PMID 41300368, 2025). "In summary, DCN may inhibit the proliferation, invasion, and metastasis of tumor cells through pathways such as EFGR and Met during the developmental process of OSCC." (PMID 40109852, 2025). "Τhe presence of decorin in tumor stroma impedes the tumorigenic process." (PMID 40542654, 2025). "N-acetylcysteine (NAC) modulates the tumor microenvironment by regulating the population of cancer-associated fibroblasts and inducing the activation of various cytokines, including CXCL12, SLIT2, and DCN." (PMID 40001479, 2025). "Certain proteoglycans, such as syndecan-1 and glypican-1, promote tumor growth and dissemination by enhancing growth factor signaling and cell migration, whereas others, including decorin and lumican, inhibit tumor progression by modulating immune responses and collagen fibrillogenesis." (PMID 41303704, 2025). "Binding of decorin to Met induces its transient activation and c‐Cbl ubiquitin ligase recruitment resulting in rapid Met proteasomal degradation and suppression of β‐catenin intracellular levels thus inhibiting Met‐driven tumor cell growth and migration." (PMID 40542654, 2025). "Notwithstanding, decorin has been shown to be an important tumour suppressor in BC." (PMID 41463344, 2025). "The expression of DCN decreases with the degree of tumor differentiation." (PMID 40109852, 2025). "In summary, these studies suggest tumor- and metastasis-suppressive roles of DCN in PC." (PMID 41470114, 2025). "Decorin interacts with several growth factors and their cognate receptors, stimulating different signalling pathways, most of which lead to growth suppression, apoptosis and inhibition of tumour angiogenesis." (PMID 41300368, 2025). "Interestingly, decorin expression in tumours is significantly reduced from the levels expressed in normal tissues." (PMID 41300368, 2025). "Moreover, DCN functions as a tumor suppressor in GC, with its expression levels significantly associated with angiogenesis and patient prognosis, suggesting its potential as a therapeutic target for GC." (PMID 39145305, 2024). "While decorin overexpression in GBM has been historically a target for virotherapy the role these therapies have on anti-tumor immunity in GBM is unknown." (PMID 38380331, 2024). "We found that rAd.DCN could promote NK cell infiltration in tumor tissues and enhance NK cell proliferation and degranulation activity in peripheral blood." (PMID 39482550, 2024). "In GBM tumor samples, decorin expression was greatly increased within the necrotic core." (PMID 38380331, 2024).
tumor (continued). "Notably, rAd.DCN + NK group 2 exhibited smaller tumor sizes than group 1 from day 16 after HCT116 inoculation, suggesting better inhibition of tumor growth." (PMID 39482550, 2024). "Decorin, in addition to being a component of the extracellular matrix, has crucial biological functions affecting cell proliferation, differentiation, apoptosis, angiogenesis, and tumor formation." (PMID 39482550, 2024). "There is some interest in exploring whether delivering decorin or boosting its expression within the tumor stroma could have a therapeutic effect in some cSCC cases." (PMID 38730679, 2024). "However, enrichment of our embryonal tumor genes was observed in the neuroendocrine and DCN-high tumor signatures, with some overlapping WNT markers in neuroendocrine and mesenchymal markers in DCN-high tumor cells." (PMID 39567475, 2024). "Whether surrounding tumor cells underwent a hypoxic transformation or preferentially sought out these decorin-influenced perivascular spaces has yet to be determined." (PMID 38805346, 2024). "We have also shown that DCN downregulation promotes tumor growth in orthotopic tumor xenografts." (PMID 38667295, 2024). "Inducing decorin expression in oncolytic adenovirus induced cytotoxicity of tumor cells." (PMID 38380331, 2024). "In this study, we hypothesized that decorin could inhibit TGF-β signaling to remodeling tumor microenvironment and CD40L further enhance the activation of immune cells." (PMID 39306655, 2024). "A second explanation is that VEGF and decorin may also alter tumour behavior due to their influence on the tumour microenvironment." (PMID 37104411, 2023). "The binding of decorin by numerous cell surface receptors results in the stimulation of autophagy and inflammation, and suppressive effects on angiogenesis and tumor formation, which are involved in tumor suppression." (PMID 37554940, 2023). "This study seeks to identify whether the presence of two proteins—vascular endothelial growth factor (VEGF) and decorin—within the tumour may assist with prediction of tumour recurrence." (PMID 37104411, 2023). "Furthermore, immunofluorescence staining showed that B.adolescentis increased the DCN+ macrophages (F4/80+DCN+) in tumor tissue of AOM/DSS model." (PMID 37464382, 2023). "The aim of the current study was to use immunohistochemistry to identify whether the presence of VEGF and decorin within a canine STS could be used to predict tumour recurrence or patient survival." (PMID 37104411, 2023). "In addition, the SLRP decorin also exhibited anti-tumorigenic properties by downregulating the release of IL-10 thereby inhibiting tumor growth." (PMID 37730606, 2023). "It was hypothesised that increased immunostaining for VEGF within a STS would predict increased tumour recurrence rates and reduced patient survival times while high decorin would predict a more favourable prognosis." (PMID 37104411, 2023). "As these receptor tyrosine kinases have essential roles in the development and progression of RCC, and TKIs for these receptors are used in the treatment of mRCC, skeletal muscle-derived decorin might have anti-tumor effects in mRCC." (PMID 38067295, 2023). "Autophagy and mitophagy are emerging as the primary mechanisms of action that fully integrate and translate decorin/RTK antagonism across diverse tissues within the tumor into the established and classical anti-tumorigenic properties attributed to this proteoglycan." (PMID 35159071, 2022). "Furthermore, DCN, ITGB1, NOTCH3 and SPARC genes were discovered to be strongly associated not only with tumor response to nCRT but also with disease-free survival; they were further used to form a four-gene expression-based risk score." (PMID 35682714, 2022). "While these two tumor-associated clusters had gene expression profiles similar to that of the DCN-high tumor cell cluster 5, they did not express HB genes including GPC3, DLK1, and DKK1." (PMID 36008377, 2022).